ZNF468 (zinc finger protein 468)
Description:
May be involved in transcriptional regulation.
Tractability: PROTAC: ubiquitination databases record sites on it.
Gene: Protein-coding gene on chromosome 19 (52,838,010 to 52,857,649, reverse strand). Ensembl gene ENSG00000204604.
Subcellular location: Nucleus
Pathways (Reactome):
Gene expression (Transcription): Generic Transcription Pathway
Gene Ontology:
Molecular function: DNA-binding transcription factor activity, RNA polymerase II-specific; RNA polymerase II cis-regulatory region sequence-specific DNA binding
Biological process: regulation of transcription by RNA polymerase II; regulation of DNA-templated transcription
Cellular component: nucleus
Genetic constraint (gnomAD): Loss-of-function variants: 8 observed, 7.22 expected, observed/expected ratio (o/e) 1.11, 90% interval 0.64 to 1.81. That is too few expected variants to judge how well the gene tolerates losing a copy. Missense variants: 608 observed, 646.54 expected, observed/expected ratio (o/e) 0.94, 90% interval 0.88 to 1.01. Synonymous variants: 218 observed, 217.6 expected, observed/expected ratio (o/e) 1, 90% interval 0.9 to 1.12.
Homologues: Orthologues: chimpanzee ZNF468 (98% identical). Paralogues in human: ZNF888 (75% identical), ZNF813 (73% identical), ZNF761 (71% identical), ZNF860 (69% identical), ZNF578 (68% identical), ZNF765 (66% identical), ZNF816 (65% identical), ZNF525 (65% identical), ZNF701 (64% identical), ZNF766 (48% identical).
Diseases named in the same sentence as ZNF468 in open-access papers:
ZNF468 is named in the same sentence as 10 diseases in open-access papers, as found by Europe PMC text mining. Sharing a sentence is not in itself a finding about the gene and the disease. The quoted sentences say what the papers report.
bladder cancer (1 paper, 2024). "Based on TCGA database, ZNF468 was overexpressed in different cancer types, including bladder cancer (BLCA), Cervical squamous cell carcinoma and endocervical adenocarcinoma (CESC), glioma (GBM), lung adenocarcinoma (LUAD), breast cancer (BC) and other cancer types." (PMID 38429817, 2024).
breast carcinoma (1 paper, 2024). "We demonstrated that ZNF468 up-regulation of TFAM not only contributed to the growth and migration of breast cancer cells but also reduced the sensitivity of the cells to cisplatin treatment." (PMID 38429817, 2024).
esophageal squamous cell carcinoma (1 paper, 2025). Esophageal squamous cell carcinoma (ESCC) is a type of esophageal carcinoma (EC) that can affect any part of the esophagus, but is usually located in the upper or middle third. "While prior research linked ZNF468 to radioresistance in oesophageal squamous cell carcinoma (ESCC), its broader role in ESCC progression remained unclear." (PMID 40702875, 2025).
oesophageal cancer (1 paper, 2025). "Bioluminescence imaging results indicated ZNF468 significantly increased the pulmonary metastatic burden of KYSE510 cells in oesophageal cancer, while the pro‐metastatic effect of ZNF468 was markedly diminished under conditions of AURKA knockdown." (PMID 40702875, 2025). "Conversely, knockdown of ZNF468 had the opposite effect, indicating ZNF468 is a promising therapeutic target for inhibiting pulmonary metastasis in oesophageal cancer." (PMID 40702875, 2025).
cancer (3 papers, 2021 to 2025). A tumor composed of atypical neoplastic, often pleomorphic cells that invade other tissues. "Our previous research identified the role of ZNF468, a zinc finger protein with emerging significance in various cancer types, in conferring radiotherapy resistance in ESCC." (PMID 40702875, 2025). "HE staining indicated that cancer tissues from the ZNF468 overexpression group exhibited more condensed nuclei, higher degrees of damage and less distinct cell boundaries." (PMID 40702875, 2025). "First, using the BEST bioinformatics analysis web tool, our findings revealed that ZNF468 mRNA levels were elevated in cancer groups across three independent cohorts (GSE53622, GSE53624, TCGA‐ESCA)." (PMID 40702875, 2025). "To verify the results in Chinese patients, we collected the normal and cancer samples from BC patients and subjected them to immunoblotting analysis of ZNF468." (PMID 38429817, 2024). "Lastly, the expression of ZNF468 was also increased in BC cancer cell lines as compared with breast immortalized cells MCF-10A." (PMID 38429817, 2024). "However, the significance of ZNF468 in the development of cancers, including BC, remains to be understood." (PMID 38429817, 2024). "The results showed that ZNF468 was highly expressed in the cancer tissues than normal tissues." (PMID 38429817, 2024). "Firstly, we investigated the clinical relevance of ZNF468 in pan-cancer." (PMID 38429817, 2024). "We reported that ZNF468 counteracts radiation‐induced G2/M checkpoint arrest and cell death in ESCC by enhancing AURKA gene expression, thereby unveiling a pivotal mechanism by which cancer cells evade the cytotoxic effects of radiotherapy." (PMID 40702875, 2025). "Our research findings may offer novel perspectives on the function of the ZNF468‐AURKA axis in ESCC and identify potential therapeutic targets within the PI3K/AKT pathway, offering a promising avenue for developing targeted therapies to combat this aggressive cancer." (PMID 40702875, 2025).
tumor (3 papers, 2022 to 2025). "Immunofluorescence showed the highest KI67 and BCL2 fluorescence intensity in tumour tissues from the ZNF468 overexpression group." (PMID 40702875, 2025). "The ZNF468 overexpression group exhibited the highest tumour volume and weight, followed by the ZNF468 overexpression combined with AURKA knockdown group, and the control group had the smallest tumours." (PMID 40702875, 2025). "ZNF468 overexpression significantly upregulated N‐Cadherin and Snail protein levels in tumour tissues, while downregulating E‐Cadherin and ZO‐1." (PMID 40702875, 2025). "Chi‐square tests revealed that patients in the high‐expression groups for ZNF468 or Aurora A had significantly higher T stages, increased lymph node infiltration and more frequent tumour metastasis." (PMID 40702875, 2025). "The PI3K/AKT activity exhibited marked upregulation in tumour tissues of the ZNF468 overexpression group, and this activation was markedly reduced following AURKA knockdown." (PMID 40702875, 2025). "Given that ZNF468 is highly correlated with tumour metastasis and lymph node infiltration in clinical samples, we subsequently explored the function of the ZNF468–AURKA axis in ESCC cell invasion and migration." (PMID 40702875, 2025). "ZNF468 overexpression significantly increased the tumour size, number of metastatic foci and malignancy of pulmonary metastases, with a marked increase in the staining intensity of the proliferation marker Ki67 and a marked reduction in the levels of the EMT marker E‐cadherin." (PMID 40702875, 2025). "Importantly, ZNF468 exerted the tumor-promoting function via up-regulation of TFAM." (PMID 38429817, 2024). "Additionally, this study focused on tumour cells and did not explore the role of ZNF468 in the tumour immune and stromal microenvironment, which is an important direction for future research." (PMID 40702875, 2025). "In addition, when we evaluated liver tissues of five patients with HCC, the protein expression of AKR1B10, ZNF468, annexin A2 (ANXA2), and CD24 was increased in tumor tissue compared with surrounding nontumor tissues." (PMID 35563425, 2022).
ZNF468 also shares sentences with these, for which no sentence is quoted: cervical squamous cell carcinoma (1 paper); endocervical adenocarcinoma (1); glioma (1); lung adenocarcinoma (1).